PVR (PVR cell adhesion molecule)
Diseases named in the same sentence as PVR in open-access papers (continued):
Sharing a sentence is not in itself a finding about the gene and the disease.
tumor (continued). "Both PVR and nectin-2 expressions are upregulated on tumor cells, which contributes to tumor recognition and killing." (PMID 33670993, 2021). "PVR is mainly expressed on dendritic cells (DCs), T cells, B cells, macrophages and all kinds of tumor cells." (PMID 33557880, 2021). "And poliovirus receptor (PVR or CD155) played crucial roles in tumor immune microenvironment and cancer development." (PMID 34150627, 2021). "All these tumor cells positively expressed PVR/CD155, in which H22 cells expressed a relatively higher level." (PMID 33581644, 2021). "Tumor cells were also found to interact with Tregs through PVR-TIGIT ligand-receptor interactions, a process that enhances the immunosuppressive function and stability of Tregs." (PMID 34367994, 2021). "These receptors compete with the costimulatory receptor DNAX accessory molecule 1 (DNAM1, or CD226) for binding to PVR and function over time to suppress T and NK cell functionality in the tumor microenvironment (TME)." (PMID 34150627, 2021). "Although the effect of azelnidipine for dual blocking of CD47/SIRPα and TIGIT/PVR interactions indeed occurs within one single model, it is hard to distinguish the contribution to the anti-tumor effects of either single blockade." (PMID 34068552, 2021). "Here, we analyzed the expression of CD47 and PVR from the GEO database and tested the existence on the tumor cell lines by flow cytometry." (PMID 34068552, 2021). "Blocking either DNAM-1 or PVR with an anti-DNAM-1 or anti-PVR antibody results in the significant inhibition of NK-mediated tumor cell lysis." (PMID 34433460, 2021). "NEFM negatively correlated with PVR (CD155), an immune checkpoint on tumor cells and interacting with CD96, CD226, and TIGIT (T cell immune receptor with immunoglobulin and ITIM domains) on TILs to modulate immune function in tumor microenvironment." (PMID 34001208, 2021). "Antibody double-blocking of TIGIT/PVR and programmed cell death protein 1 (PD-1)/programmed death-ligand 1 (PD-L1) has been demonstrated to produce synergistic effects in both tumor models and clinical trials." (PMID 34367994, 2021). "The CD47/SIRPα and TIGIT/PVR signaling pathway jointly contribute to the immunosuppressive tumor microenvironment." (PMID 34068552, 2021). "We observed increased expression of 5 immune suppressive genes including PVR (CD155), TGFB1, NT5E (CD73), VEGFA, and CD276 (B7-H3) in 9p21-loss tumors across multiple tumor types/subtypes when compared to 9p21-WT tumors." (PMID 34556668, 2021). "Here, we examined the over-expression of CD47 and PVR in a broad spectrum of cancers and tumor cell lines." (PMID 34068552, 2021). "Here, an elevated expression of CD47 and PVR was observed in tumor tissues and cell lines analyzed with the GEO datasets and by flow cytometry, respectively." (PMID 34068552, 2021). "It is barely expressed in normal human tissues, but many tumor cell lines and primary malignancies highly express PVR." (PMID 32117298, 2020). "The novel immune checkpoint TIGIT expressed on NK cells, activated CD8+ T cells, effector CD8+ T cells and regulatory T cells (Tregs), and suppressed the anti-tumor immune response by interacting with PVR." (PMID 32894141, 2020). "PVR was over-expressed in many tumor tissues and cancer cell lines, making it a promising therapeutic target." (PMID 32894141, 2020). "Although constitutively expressed on most normal tissues, Nectin-2 and PVR are found upregulated on tumor cells." (PMID 32069911, 2020). "In this context, gene expression analysis from The Cancer Genome Atlas (TCGA) datasets showed reduced expression of DNAM1 and overexpression of its ligand PVR in different tumor types." (PMID 32178479, 2020). "More importantly, by analyzing the GSE41258 dataset, we observed that the expression level of PVR was gradually upregulated during the tumor development from normal colon to polyps and primary tumors." (PMID 32894141, 2020).
tumor (continued). "Consistently, PVR overexpression was correlated with tumor progression and unfavorable prognosis in different cancer cell types." (PMID 32069911, 2020). "CD155 is a transmembrane glycoprotein, also known as PVR, that is highly expressed in many tumor cell lines and primary malignancies." (PMID 32640575, 2020). "PVR and Nectin-2 are expressed by tumor cells as well as myeloid cells, while TIGIT, CD96, and DNAM-1 are expressed on effector lymphoid cells." (PMID 32489646, 2020). "The novel immune checkpoint TIGIT/PVR plays critical roles in suppressing the anti-tumor effects of CD8+ T and NK cells, and dual blockade of TIGIT/PVR and PD-1/PD-L1 by antibody can elicit synergistic effects in tumor models and clinical trials." (PMID 32894141, 2020). "Expression of IDO and PVR in tumor nests was significantly higher in NE‐low primary tumors (vs NE‐high, P < 0.05)." (PMID 32506804, 2020). "Recently, it was reported that PVR is highly expressed in SCLC cell lines with minimal expression observed on immune cells in the tumor microenvironment." (PMID 32506804, 2020). "Inhibition of Ub and SUMO pathways increases Nectin2 and PVR surface expression and renders tumor cells more sensitive to NK cell-mediated killing." (PMID 31736972, 2019). "We therefore propose a novel TIGIT/PVR interaction mode that tumor intrinsic TIGIT delivers inhibitory signals to CD8+ T cells and NK cells by engaging with PVR." (PMID 30555485, 2018). "These functions are absolutely different from the effects of TIGIT on T cells in transmitting inhibitory signal and mediating tumor evasion through the ITIM motif by ligation with PVR." (PMID 30555485, 2018). "TIGIT counterbalances CD226-mediated T-cell activation by competing with CD226 for binding to PVR, a receptor that is expressed in multiple tumor types." (PMID 30400822, 2018). "In this context, different studies showed that PVR improve tumor cell invasion, being localized at the migrating cellular front together with actin and alphav-integrin, known mediators of motility and adhesion." (PMID 28456791, 2017). "On the other hand, it has been shown in primary glioblastoma that endothelial cells of proliferating tumor vessels express PVR at higher surface densities as compared to normal vessels." (PMID 24575100, 2014). "In relation to DNAM-1, in vitro studies have shown that this activating receptor triggers NK cell-mediated killing of a range of tumor cells expressing PVR and/or Nectin-2." (PMID 24432022, 2014). "In animal models, targeting of PVR with an attenuated oncolytic poliovirus induced tumor regression and elimination." (PMID 24575100, 2014). "Furthermore, it has been observed that PVR upregulation is related to an increased metastatic potential of tumor cells." (PMID 40369504, 2025). "Immune checkpoints contribute to the malignant progression of tumor by regulating tumor immune microenvironment and promote malignant behaviors such as tumor cell proliferation and metastasis, including programmed cell death 1 (PD-1), poliovirus receptor (PVR), SIRPA and other immune checkpoints." (PMID 41024301, 2025). "Both PVR gene expression and serum levels were strongly and positively correlated with β2-microglobulin (rs = 0.813, p < 0.001; r = 0.441, p = 0.001, respectively), emphasizing its direct link to tumor burden." (PMID 40369504, 2025). "Additionally, by upregulating PVR expression in tumor cells, VPS25 activated the immunosuppressive PVR-TIGIT signaling axis, thereby facilitating immune evasion." (PMID 40149859, 2025). "This pro-tumor stromal configuration, aside from its close association with cancer cells, promotes an immunosuppressive TME by releasing inhibitory signals, particularly PVR, which engages with TIGIT on immune cells and suppresses their functions." (PMID 40107247, 2025).
tumor (continued). "In CRC, ADAR-mediated RNA editing at 3ʹ-UTR of PVR could upregulate its expression by increasing the RNA stability, leading to tumor- and immune-related gene functions and pathways in CRC." (PMID 39126156, 2025). "Thus, future studies should explore biomarkers that represent TIGIT/PVR signaling activity in tumor tissues along with PD-L1 expression levels." (PMID 39847233, 2025). "Mechanistic studies have revealed that elevated PVR expression in tumor cells, through binding to DNAM-1, induces tyrosine phosphorylation of DNAM-1’s cytoplasmic tail, which subsequently initiates its ubiquitin-dependent internalization and proteasomal degradation pathway." (PMID 40463500, 2025). "In addition to its role as a prognostic marker, the overexpression of the PVR gene and its serum levels in MM points to its implication in immune evasion and tumor aggressiveness by interacting with immune checkpoint receptors such as TIGIT and CD96." (PMID 40369504, 2025). "PVR was thought to be expressed by antigen-presenting cells and tumor cells." (PMID 40607392, 2025). "Notably, tumor-infiltrating NK cells expressing the inhibitory receptor KIR2DL5 are frequently observed in malignancies with high PVR expression." (PMID 40977889, 2025). "TIGIT is a CD8 + effector memory T cell inhibitory molecule that interacts with PVR to inhibit anti-tumor immune responses, and PVRL1/TIGIT inhibitors and anti-PD1 antibodies could be developed to treat HCC52." (PMID 38890507, 2024). "In clinical samples, PVR was also expressed well in tumor epithelial cells of HGSOC." (PMID 39156900, 2024). "DNAM1 has a soluble form and can bind to PVRL2 or PVR on tumor cells." (PMID 39156900, 2024). "Tiragolumab is a fully human IgG1/kappa anti-TIGIT monoclonal antibody with an intact Fc region that prevents the binding of TIGIT to PVR that is well tolerated and has demonstrated promising anti-tumor activity in combination with the PD-L1-inhibitor atezolizumab in phase I and II clinical trials." (PMID 38206370, 2024). "However, none of these reports have directly demonstrated a role for PVRL2 or PVR in tumor immune mechanisms." (PMID 39156900, 2024). "Indeed, myeloid cells associated with a favourable clinical response expressed transcripts associated with tumour-residing CCR7+ DCs, including CCR7, CD274, IL15, PVR and CD70." (PMID 38267413, 2024). "High density of CD3+ (HR: 0.555, p=0.018), CD20+ (HR: 0.482, p=0.002) and CD163+ (HR: 0.514, p=0.039) cell infiltrates was associated with better RFS as well as high levels of PD-L1 and PVR in tumor cells (HR: 0.626, p=0.034 and HR: 0.538, p=0.034, respectively)." (PMID 39723208, 2024). "Moreover, we observed that the tumor cell marker gene EPCAM exhibited more similar spatial localization with the NECTIN2 than PVR gene in lepidic pattern, which is consistent with the results of scRNA-seq data." (PMID 39474422, 2024). "Primed CD226-deficient CD8 + T cells elicited a reduced cytotoxic effect on PVR-expressing mouse tumor cell lines, whereas CD226 deficiency did not affect the expansion of CD8 + T cells upon co-culture with mouse leukemia RMA cells that did not express PVR66." (PMID 39349829, 2024). "We also found that an upregulation of the NK-cell cytotoxicity trigger molecule DNAM-1 on γδ T-cells expanded after exercise and β2-AR agonist infusion, and its ability to ligate with the PVR and Nectin-2 expressed by leukemic targets, were directly involved in the anti-tumor response." (PMID 38592213, 2024). "To determine whether tumor-derived Pvf1 activates PVR signaling pathway in MTs, we decreased Pvf1 expression in the gut stem cells of Yki flies (esg> ykiact+ Pvf1-i)." (PMID 38336808, 2024). "In addition, even though PVRL2 and PVR are known to be expressed on both tumor cells and antigen-presenting cells (especially macrophages), most studies have focused on the expression on tumor cells." (PMID 39156900, 2024). "PVR expression is also higher in the tumor than adjacent normal tissue." (PMID 39156900, 2024).
tumor (continued). "This is an inhibitory receptor expressed on lymphocytes that interacts with its complementary target, CD155 (Polio Virus Receptors, PVR or NECL-5) on the surface of antigen-presenting cells or tumour cells to suppress T and natural killer (NK) cell anti-tumour responses." (PMID 37325585, 2023). "However, PVR and Nectin2 are also recognized by inhibitory receptors that are upregulated in tumor microenvironment and can counteract DNAM-1 activation, leading to NK cells hypo-functionality." (PMID 37760586, 2023). "As PVRAP interacts with PVR, we propose that PVRAP could act as a tumor suppressor by regulating PVR activity, similar to the relationship between EGFRAP and EGFR." (PMID 37510408, 2023). "In addition, IMiDs make tumor cells more susceptible to NK cell killing by upregulating ligands for NKG2D, DNAM1, MICA, and PVR in tumor cells." (PMID 37539051, 2023). "The ITIM confers to PVR the ability to trigger the activation of different signaling pathways leading to cell proliferation, inhibition of adhesion and the induction of cell migration, representing an intrinsic advantage for tumor growth and spread." (PMID 37760586, 2023). "The expression of α and δ isoforms on the membrane of tumor cells may impact PVR function, since only α isoform can transduce intracellular signals thanks to the presence of an ITIM motif in its cytoplasmic domain." (PMID 37760586, 2023). "Third, the TIGIT on the surface of tumor-infiltrating CD8+T cells competitively binds to the PVR on the surface of tumor cells or dendritic cells, resulting in the failure of T cell-activated receptor CD226 to bind to PVR, thus inhibiting the activity of T cells." (PMID 37035135, 2023). "Additionally, there was no longer a significant difference in IFNγ expression between PVR− or PVR+-K562 cell restimulation when anti-TIGIT antibodies were present in the initial tumor co-culture, indicating that the initial difference was TIGIT-dependent." (PMID 37345049, 2023). "In conclusion, PVR might be an important regulator of tumor immune cell infiltration and a valuable prognostic biomarker in HCC." (PMID 36552960, 2022). "Additionally, patients with elevated PVR expression showed a higher tumor burden based on the percentage of bone marrow plasma cells and β2-microglobulin, the levels of which are reportedly correlated with tumor stage, than those with lower PVR expression." (PMID 35625835, 2022). "In this context, it is important to again emphasize that PVR is widely expressed, even by most tumor cells, suggesting that CD226 activation may participate in the T cell effector activity more so than CD28, whose activating ligand is limited to immune cells." (PMID 35263569, 2022). "Additionally, PVR present on the cancer cell surface reportedly promotes tumor invasiveness, and its upregulation in tumor-infiltrating myeloid cells impairs antitumor T lymphocyte and natural killer (NK) cell functions, thereby suppressing antitumor immunity." (PMID 35625835, 2022). "KIR2DL5 inhibited NK cell function and mediated PVR+ tumor immune resistance." (PMID 36377656, 2022). "In this report, we clearly showed that both Fc-silent and -competent BGB-A1217 could elicit NK cell activation in the presence of PVR+ tumor cells." (PMID 35273608, 2022). "Tumor cells mainly secreted PVR and NECTIN2 to act on the TIGIT receptor." (PMID 36685571, 2022). "PVR is upregulated during tumor progression and promotes tumor proliferation and migration." (PMID 35625835, 2022). "Since TIGIT could act as a negative regulator of NK cell functions, it represents an ideal molecule that can be targeted in checkpoint blockade strategies to boost NK tumor-immunity against CD155/PVR expressing cancers." (PMID 36291830, 2022). "Notably, IMiDs such as lenalidomide and pomalidomide are able to potentiate NK cell-mediated ADCC by increasing the expression of NK-cell activating ligands MICA and PVR/CD155 on MM cells, which facilitates tumor recognition and killing by NK cells." (PMID 36421358, 2022).
tumor (continued). "In addition, it is worth noting that PVR can serve as an important immunoregulatory protein and play a vital role in tumor cell immune surveillance and immune escape." (PMID 36552960, 2022). "Intriguingly, we observed molecular characteristics more similar to immunophenotypic variances occurring in vivo and not fully comprehended in traditional 2D culture conditions, such as the IFN-γ-induced negative regulation of PVR (CD155) expression on tumor cells after 7 days of 3D culture." (PMID 35205760, 2022). "This may be important in the context of TILs expressing varying levels of CD28, CD226, PD-1, and TIGIT, and myeloid or tumor cells expressing PD-L1 and PVR." (PMID 35263569, 2022). "Therefore, to connect these data on tumor cell death with NK cell activation, we used B16F10 cells deficient in expression of CD155/PVR/Necl5 and CD112/Nectin2 and (Necl5 and Nectin2, hereafter), the ligands for the activating receptor DNAM-1 on NK cells." (PMID 35113018, 2022). "We demonstrated that KIR2DL5 mediated PVR+ tumor immune resistance to NK cell killing." (PMID 36377656, 2022). "Moreover, the PVR level in HCC correlated with the level of tumor-infiltrating immune cells and multiple markers of immune cells." (PMID 36552960, 2022). "Similarly, NK-mediated lysis of tumor cells is enhanced after DNAM-1 (in NK cells) interacts with PVR or Nectin-2 (in target cells), whereas this effect is inhibited by treatment with a mAb targeting DNAM-1 or its receptor." (PMID 34433460, 2021). "It is reported that a CD47/SIRPα blockade and TIGIT/PVR blockade could elicit significant anti-tumor responses." (PMID 34068552, 2021). "Here, we firstly demonstrated that azelnidipine dually targeting SIRPα and PVR could be a promising anti-tumor modality in cancer immunotherapy." (PMID 34068552, 2021). "As such, blocking this interaction with PVR in the TME might be an effective therapy for tumor control." (PMID 34150627, 2021). "Furthermore, in tumor segments of patients with a combination of solid and acinar morphological growth patterns, PVR was higher expressed in solid growth pattern compared to acinar growth pattern (P=0.00736)." (PMID 34102454, 2021). "We also investigated the expression of CD47 and PVR on the tumor cell lines by flow cytometry." (PMID 34068552, 2021). "Based on the mechanism underlying TIGIT-mediated regulation of anti-tumor immune responses, efforts have been made to enhance T or NK cell activity by blocking TIGIT binding to its ligands, PVR and nectin-2, with monoclonal antibodies (mAbs) for therapeutic interventions." (PMID 33670993, 2021). "In many preclinical models, the anti-tumor activity is studied by blocking the TIGIT/PVR axis." (PMID 34631507, 2021). "Meanwhile, emerging evidence showed that therapies targeting PVR/TIGIT/CD96 pathways could enhance anti-tumor capacity across certain cancer types." (PMID 34150627, 2021). "A TIGIT/PVR blockade could reverse the exhaustion of both T cells and NK cells, resulting in significant and durable anti-tumor effects." (PMID 34068552, 2021). "In accordance with this finding, a differential level of the ligand expression, such as PVR and PD-L1, or an increase in the binding affinity of TIGIT to PVR under an acidic tumor microenvironment has been recently identified to contribute toward the sensitivity of tumor cells to TIGIT blockade." (PMID 33670993, 2021). "By ligand interaction, TIGIT is able to inhibit lymphocytes activity through different mechanisms of action including modulation through its intracellular tail after binding to PVR, induction of PVR signaling in adjacent dendritic or tumor cells, and inhibition of CD226 signaling." (PMID 33782477, 2021). "However, tumor cells evade immune surveillance and induce T cells and NK cells exhaustion by overexpressing PVR." (PMID 33557880, 2021). "TIGIT/PVR exerts a key role in inhibiting the anti-tumor effects of CD8 T cells and NK cells." (PMID 34367994, 2021).